BRAF (B-Raf proto-oncogene, serine/threonine kinase)
Diseases named in the same sentence as BRAF in open-access papers (continued):
Sharing a sentence is not in itself a finding about the gene and the disease.
melanoma (continued). "Therefore, encorafenib plus binimetinib showed improved efficacy and a better tolerability profile than encorafenib or vemurafenib, offering a potential treatment option for patients with BRAF-mutant melanoma." (PMID 39582535, 2024). "While Comprehensive Genomic Profiling of solid tumours has been approved as a companion diagnostic, still no approved predictive biomarkers are available for Melanoma aside from BRAF mutations and the controversial Tumor Mutational Burden." (PMID 38184610, 2024). "Furthermore, our work shows that HDAC10 depletion and resultant SPARC upregulation led to repressive melanoma cell growth and increased vulnerability to BRAF inhibition in resistant cells." (PMID 38650694, 2024). "Both ICIs and BRAF/MEKi have become the standard of care for melanoma." (PMID 38358050, 2024). "This suggests that while the BRAF mutation is a crucial step, it is not solely decisive in the transition from a benign nevus to an aggressive melanoma." (PMID 38534742, 2024). "These contrasting results might be due to employing melanoma cell lines with differential CSPG4 expression, variable susceptibility to BRAF inhibition, or the use of different antibody clones and isotypes." (PMID 39409881, 2024). "In addition, cases of SCC and KA-like lesions have been reported post-treatment in patients taking vemurafenib (BRAF inhibitor initially designed to treat malignant melanomas)." (PMID 39449378, 2024). "Immune checkpoint inhibitors and BRAF-targeted therapy each improve survival in melanoma." (PMID 38907159, 2024). "Their vaccine consisted of six non-mutated melanoma-specific helper peptides (6MHP) and an additional BRAF-V600E peptide combined with two agents that enhance APC function and activation, toll-like receptor 3 (TLR3) agonist and CD40 agonist." (PMID 39682188, 2024). "BRAF mutation analysis is recommended for patients with stage III–IV melanoma according to the guidelines because it influences whether patients can receive BRAF‐targeted treatment." (PMID 39624750, 2024). "Triple combination therapy or triple therapy (inhibiting BRAF, MEK and PD1/PDL1 axis) showed significantly longer progression-free survival compared to BRAF + MEK combination therapies (HR = 0.76; 95% CI 0.64–0.9), but similar objective and complete response rates in BRAF-mutated melanoma." (PMID 39684531, 2024). "In addition, the presence of TERT promoter mutations is often associated with co-occurring mutations in BRAF or NRAS, indicating a synergistic effect on melanoma progression." (PMID 39200315, 2024). "Although FAK activates RAF/MEK/ERK mitogen-activated protein kinase (MAPK) signaling cascade to promote cell survival, in half of melanomas, including A375 and C32 cells, the function of FAK in triggering ERK is attenuated due to the activating BRAF V600E mutation." (PMID 39274939, 2024). "Among patients aged 66+ years with stage 3 melanoma, increases in survival trends were observed beginning a few years later in 2013, which may be due to slower adoption of ICIs and BRAF/MEK inhibitors." (PMID 39194340, 2024). "Combined BRAF and MEK inhibitors, as compared with BRAF inhibitors alone, should be delay the emergence of resistance and should be reduce toxic effects in patients who have melanoma with BRAF V600E or V600K mutations." (PMID 39776585, 2024). "To explore the correlation between BRAF(V600E) and differential gene expression in colon cancer, thyroid cancer, and melanoma, we analyzed gene expression in the BRAF(V600E) mutant group and the wild-type BRAF group of colon cancer, thyroid cancer, and melanoma patients, based on the TCGA database." (PMID 39052013, 2024). "This dependence on glycolysis sensitizes BRAF-driven melanomas to BRAF inhibitors." (PMID 38339003, 2024). "Given that approximately 50% of melanomas harbor BRAF mutations, our patient's negative status eliminated the possibility of employing BRAF inhibitors, a common treatment for positive cases." (PMID 39119371, 2024).
melanoma (continued). "Subsequently, DTP cells have been identified in various experimental models after targeted therapy, including additional EGFR‐mutant NSCLC cell lines, MET‐amplified gastric cancer, BRAF‐mutant melanoma, prostate cancer, colorectal cancer, and HER2‐positive breast cancer." (PMID 39184861, 2024). "Inhibitors of BRAF and MEK have shown clinical benefit when used in combination, initially in BRAF V600-mutated melanoma for which the following three associations are approved to date by the FDA: vemurafenib/cobimetinib, dabrafenib/trametinib, and encorafenib/binimetinib." (PMID 39064466, 2024). "Given the significant crossover in genomic mechanisms of carcinogenesis, it may be pertinent to screen for thyroid nodules via physical examination in patients with a history of BRAF-positive melanoma." (PMID 39036614, 2024). "We observed that the ATP-competitive inhibitor PHA-665752 and the non-ATP-competitive, clinical phase II inhibitor ARQ197 (tivantinib) elicited response in BMCs and conventional melanoma cell lines irrespective of the BRAF/NRAS mutation status." (PMID 38386085, 2024). "Overall, the site of metastasis and serum LDH level appear to be strong determinants of melanoma prognosis, independent of BRAF mutational status and type of treatment." (PMID 39272837, 2024). "Based on these results, combination TIL and BRAF inhibitor therapy could have synergistic effects against melanoma tumors." (PMID 39682188, 2024). "While early stage (I-IIA) melanoma has 5-year overall survival rates of greater than 90%, it worsens in more advanced disease Melanoma arises in melanocytes due to a combination of genetic predisposition (CDKN2A, CDK4) and acquired mutations (BRAF, MEK) from ultraviolet light-induced damage." (PMID 39602056, 2024). "To date, the effect of BRAF inhibitors on melanoma cells is quite well described." (PMID 39175042, 2024). "Overall, our findings highlight the crucial role of eIF4F in regulating ERK signaling flux and suggest that pharmacological eIF4F inhibitors can disrupt the negative feedback control of MAPK activity in melanomas with BRAF and NRAS activating mutations." (PMID 39436655, 2024). "In this follow-up analysis of real-world data, we aimed to investigate the clinical management and outcomes of advanced melanoma patients in a tertiary referral center in Switzerland approximately a decade after the introduction of ICIs and BRAF/MEKi into clinical use." (PMID 38473216, 2024). "Drug-tolerant cells, which are also referred to as drug-tolerant persisters, have also been found for other targeted therapeutic treatments such as those for BRAF-mutant melanoma, androgen-receptor-driven prostate cancer, and HER2-amplified breast cancer, as well as chemotherapy." (PMID 38473364, 2024). "Similarly, CuET treatment also induced ROS in our BRAF WT melanoma models, and ROS quenchers or potent copper chelators abrogated the therapy-enhancing effect of CuET on the MEKi." (PMID 38263136, 2024). "A subset of advanced melanoma patients have a mutant BRAF protein." (PMID 38473384, 2024). "In vivo BRAF-mutant melanoma models with fluorescent markers to track stage-specific changes in macrophages under targeted therapy with BRAFi/MEKi, showed a rise in CCR2+ macrophage infiltration at the onset of a drug-tolerant persister (DTP) state after several weeks of treatment." (PMID 38533720, 2024).
melanoma (continued). "Additionally, anti-tumor activity was reported in a child with a recurrent spindle cell sarcoma harboring a novel SNX8::BRAF fusion and in three adult patients with melanomas harboring different BRAF fusions." (PMID 37978284, 2024). "Melanoma, CRC, and NSCLC also exhibited a higher proportion of Class 3 BRAF mutations in males." (PMID 38275886, 2024). "Furthermore, expression of the macrophage inhibitory cytokine-1 (MIC-1), a member of the TGF-β family regulated by mutant BRAF melanomas, is enhanced in the TME and the patient circulation." (PMID 38533720, 2024). "However, there is no clear evidence indicating that BRAF status impacts outcome in advanced melanoma treated with pembrolizumab, and patients with both BRAF wild‐type and BRAF mutant melanoma have been shown to benefit from treatment." (PMID 38529706, 2024). "Intracranial ORR was 42% in BRAF-mutant melanomas and 27% in BRAF-WT melanomas." (PMID 39727691, 2024). "SOX10 expression was proposed to be suppressed by therapy-related factors, i.e., radiation treatment in a glioblastoma mouse model, TGF-β-mediated stress signaling activated by irradiation, hypoxia, or TMZ in human glioma cells, and BRAF inhibition in melanoma patients." (PMID 39285246, 2024). "1H MRS-derived metabolic biomarkers indicate melanoma response or resistance to BRAF inhibition." (PMID 38254853, 2024). "Although MAPK pathway mutations can induce the proliferation of melanocytes within a nevus, it is obvious that not all nevi (bearing BRAF mutations) will turn to melanoma." (PMID 38396984, 2024). "The TCGA network, employing whole exome sequence examination in patients diagnosed with local and/or advanced melanoma, recognized four unique genomic subtypes: those with mutations in NF1, mutations in BRAF, mutations in NRAS, and those categorized as triple wild type." (PMID 38539531, 2024). "However, few studies have directly compared hand-to-hand BRAF/MEK inhibitors vs. anti-PD1 agents in resected BRAF-mutant melanoma patients." (PMID 39727691, 2024). "Therefore in the previous research, we have obtained and characterized two melanoma cell lines resistant to the BRAF inhibitor vemurafenib." (PMID 39175042, 2024). "CTHRC1 inhibitors could potentially be used as adjuvant treatment alongside BRAF(V600E)-targeted drugs in BRAF(V600E) mutant colon cancer, thyroid cancer, and melanoma." (PMID 39052013, 2024). "Such a combination is detected in up to 18% of BRAF non-V600 melanomas." (PMID 39340537, 2024). "When choosing immunotherapy versus targeted therapy for BRAF-mutant melanoma in the advanced setting, ipilimumab and nivolumab could be a better option over targeted therapy." (PMID 38748192, 2024). "Of the dabrafenib and trametinib-resistant melanoma patients, one out of five were found to have a BRAF splicing alteration associated with a lack of exons 2–10." (PMID 38539548, 2024). "Studies have shown that the activation of mTOR prevents cellular senescence caused by BRAF mutations, but this pathway does not appear to lead directly to the development of malignant melanoma." (PMID 39161800, 2024). "V-Raf murine sarcoma viral oncogene homolog B1 (BRAF) and MEK are two critical oncogenic proteins within the MAPK signal transduction cascade, and their activating mutations are prevalent in a wide array of cancers including melanoma and colorectal cancer." (PMID 39057138, 2024). "In certain melanomas and colorectal cancers, inhibition of mutant BRAF suppresses oncogenic ERK signals but simultaneously relieves ERK-dependent negative feedback of RTKs, resulting in strong epidermal growth factor receptor (EGFR) stimulation, cell survival, and drug resistance." (PMID 39488530, 2024). "Thus, novel combinations are needed to increase the efficacy and duration of response to MEKi in BRAF WT melanoma." (PMID 38263136, 2024).
melanoma (continued). "Before the development of ICIs and BRAF/MEKi, when the prognosis of advanced melanoma was dismal, there were few discussions on whether treatment should be continued after a long‐term response." (PMID 38358050, 2024). "One case report provided an example of a successful surgical resection of a patient’s metastatic melanoma to the adrenal gland, negative for BRAF mutation, whose primary melanoma site and subsequent lung metastases had already been resected years prior." (PMID 39119371, 2024). "Although statistical validation of our findings would require analyses of larger sample cohorts, the data from our samples suggest significantly higher LOXL3 fold change gene expression in BRAF+ melanoma than in BRAF– melanoma, dysplastic nevi, and melanoma in situ." (PMID 39273022, 2024). "Similarly, elevated MAP3K3 expression supported the prosurvival activity of YAP in BRAF inhibitor-resistant melanoma cells." (PMID 38622197, 2024). "In melanomas, the MAPK pathway is activated by mutations in BRAF and NRAS genes." (PMID 39195270, 2024). "In addition, distant metastases were significantly more likely to be associated with elevated serum S100B levels in patients with BRAF mutant melanoma than in patients with BRAF wild-type melanoma." (PMID 39272837, 2024). "In addition, miR-876 overexpression sensitized melanoma cells to vemurafenib treatment, suggesting a rationale for combinatorial therapy involving miR-876 overexpression and BRAF inhibition." (PMID 39138582, 2024). "To investigate whether the treatments directly affected intracellular levels of Cu2+ in BRAF WT melanoma cells, we tested whether trametinib, CuET or the combination changed intracellular Cu2+ concentrations." (PMID 38263136, 2024). "In addition to a potential lineage association, oncogenic KRAS signaling is the best predictor for a tumor suppressive role of AMBRA1 in LUAD, and oncogenic BRAF signaling correlates with AMBRA1 tumor suppressive activity in melanoma in DepMap." (PMID 39617889, 2024). "Improved survival outcomes in BRAF mutant melanomas may be related to disease biology in addition to the availability of multiple therapeutic avenues." (PMID 38611025, 2024). "scRNA-seq of melanoma cells isolated from patient-derived xenograft mouse models treated with BRAF/MEK inhibitors identified four transcriptional states with differential MITF activity representative of the pigmented, invasive, neural crest stem cell and starved phenotypes." (PMID 38241976, 2024). "A large retrospective cohort study from 5 international melanoma centers reported that the median overall survival of advanced melanoma patients after resistance to BRAF inhibitors was only 2.9 months, highlighting an urgent and unmet medical need for more effective targeted therapeutics." (PMID 38874532, 2024). "Indeed, BRAF and MEK co-inhibition has been shown to counteract the immunosuppressive function of the oncogenic mutant BRAF V600E and to enhance adoptive cell transfer immunotherapy in a mouse model of BRAF V600E-driven melanoma." (PMID 38420122, 2024). "Melanomas with mutated BRAF are usually located on parts of the body not typically exposed to the sun." (PMID 38672652, 2024). "Additionally, the SECOMBIT trial demonstrated that sequential immunotherapy (nivolumab plus ipilimumab) and targeted therapy (encorafenib plus binimetinib) provide clinically significant survival benefits in patients with BRAF-mutant melanoma." (PMID 38474231, 2024). "BRAF(V600E)-targeted drugs (including Vemurafenib, PLX-4720, Dabrafenib, and SB-590885) have been effectively used for the treatment of colon cancer, thyroid cancer, and melanoma with the BRAF(V600E) mutation." (PMID 39052013, 2024). "Immunotherapy with nivolumab or pembrolizumab should be offered to patients with resected stage IIB/C BRAF wild-type vulvar melanomas, while either of these agents, or a combination of dabrafenib and trametinib may be considered for BRAF-mutant cases." (PMID 39797152, 2024).
melanoma (continued). "Importantly, these substitutions initiate a constitutional activation of the MAPK pathway, leading to the overactive growth of BRAF-mutant melanoma cells." (PMID 38732242, 2024). "In various cancers, including colon cancer, melanoma, and thyroid cancer, tumors harboring mutations in the KRAS (Kirsten rat sarcoma viral oncogene homolog) and BRAF (encoding B-Raf protein) genes tend to be associated with a more aggressive behavior compared to wild-type tumors." (PMID 38391958, 2024). "In a BRAF-mutated melanoma mouse model, adaptive resistance alterations of CAFs leads to matrix production, remodeling and subsequent FAK activation within tumor cells to promote melanoma survival." (PMID 39034922, 2024). "COMBI-i (NCT02967692) is a three-part randomized phase III trial testing investigational anti-PD-1 antibody spartalizumab in combination with dabrafenib plus trametinib (Sparta-DabTram) vs. placebo plus dabrafenib and trametinib (placebo-DabTram) in patients with BRAF V600 advanced melanoma." (PMID 39534873, 2024). "Additionally, 2, 4, and 1 NF1-mutant melanomas harbored chromothripsis events spanning BRAF, NRAS, and NF1, respectively." (PMID 38758740, 2024). "We first track BRAF kinase activity conformational changes upon melanoma drug binding." (PMID 39088265, 2024). "While established data now exist for anti-PD-1-based immunotherapy in the treatment of high-risk stage II melanoma, data are still lacking on the value of targeted therapies (i.e., BRAF inhibitors and MEK inhibitors)." (PMID 39123418, 2024). "Previous evidence supports the notion that macrophages could trigger resistance in BRAF-mutant melanoma." (PMID 38942020, 2024). "Furthermore, predicted drug sensitivities revealed potential repurposing candidates for new 100 pediatric cancer cell lines, and predicted gene effect scores reflected BRAF resistance in melanoma cell lines." (PMID 39240541, 2024). "It has been shown that the introduction of BRAF V600E mutation into mice carrying the Mc1r mutation leads to a high incidence of invasive melanomas without providing or inducing additional gene aberrations or ultraviolet exposure." (PMID 38183457, 2024). "The data on melanoma CAFs are still emerging, especially relative to breast cancer, and existing data often reflect the push to address treatment resistance to checkpoint blockade therapy and drugs targeting melanoma specific mutants such as BRAF." (PMID 38525245, 2024). "Furthermore, BRAF-only testing is performed for all recurrent melanomas, acral melanomas, and melanomas with spitzoid features." (PMID 39661469, 2024). "Furthermore, our group showed an above-average presence of nodular and ulcerated melanomas, leading to a higher T-stage and, consequently, an advanced tumor stage, necessitating BRAF analysis." (PMID 39125519, 2024). "The data collected in our real-world evidence cohort of BRAF mutated patients reflect a diverse population of melanoma patients older than 65 years, which are usually not fully represented in pharma based clinical trials." (PMID 39207855, 2024). "However, we did not observe any associations between the most frequent somatic mutations (BRAF, CDKN2A, PTEN, NRAS) and Treg infiltration in AYA melanoma." (PMID 38589406, 2024). "Moreover, VP effectively restored BRAF inhibitor suppression and attenuated growth of resistant melanoma at low concentrations." (PMID 38635031, 2024). "BRAF as a target for melanoma and other solid tumors has recently been reviewed in detail." (PMID 38927967, 2024). "Specifically, the BRAF inhibitor dabrafenib (Tafinlar, Novartis Pharmaceuticals Corp) and MEK inhibitor trametinib (Mekinist, Novartis Pharmaceuticals Corp), which were shown to be efficacious in patients with metastatic BRAF-mutant melanomas, were brought into the adjuvant setting." (PMID 39123418, 2024).